INS (insulin)
Diseases named in the same sentence as INS in open-access papers (continued):
Sharing a sentence is not in itself a finding about the gene and the disease.
liver (74 papers, 2008 to 2026). "However, NEFA in the insulin group on day 7 postpartum was significantly lower than that in the control group, and it consistently remained below 0.70 mmol/L, which indicates a significant reduction in the risk of ketosis and fatty liver in cows." (PMID 39881718, 2024). "The mechanism of fatty liver induced by an HFD is known to involve insulin resistance in adipose tissue and skeletal muscle leading to excessive circulating FFAs, which influx to the liver and are stored as TGs." (PMID 40332475, 2025). "Exogenous E and P reduce bile acid production and serum levels of insulin, glucose, and insulin-like growth factors, all of which have been postulated to enhance colorectal carcinogenesis." (PMID 40153580, 2025). "The glucagon-like peptide (GLP-1) receptor agonists and sodium-glucose cotransporter-2 (SGLT-2) inhibitors have been developed as new glucose-lowering drugs, which can improve fatty liver via an insulin-independent glucose-lowering effect." (PMID 38701096, 2024). "More recently, an egg white-derived peptide was reported with the potential to ameliorate non-alcoholic fatty liver in insulin resistant mice." (PMID 38156281, 2023). "The results showed a significant decrease in the prevalence of non-alcoholic fatty liver across the tertiles for both fasting and postprandial glucagon to insulin ratios." (PMID 37762748, 2023). "Our results are in accordance with findings from a previous study that swimming exercise can activate PPAR-γ expression in the liver tissue and simultaneously increase CPT-1 and MCAD levels, and thereby relieve liver lipid disorders in insulin-resistant mice." (PMID 36295841, 2022). "Nearly a century has passed since T1D was first identified as a disease of the pancreas and successfully treated with insulin." (PMID 32927606, 2020). "This hepatic insulin action appears to be (largely) preserved in liver IR." (PMID 38493102, 2024). "Our findings show that this postprandial lipid profile is specifically related to liver IR, and less so to muscle IR, despite similar body fat percentage, liver fat, and whole-body insulin sensitivity, and lower systemic low-grade inflammation, as indicated by lower circulating CRP levels." (PMID 38493102, 2024). "In conclusion, individuals with liver IR or muscle IR have distinct postprandial plasma metabolite responses after a mixed meal, despite similar fasting metabolite profiles, body fat percentage, and whole-body insulin sensitivity." (PMID 38493102, 2024). "Insulin and glucagon regulate lipolysis and we previously showed that serum glucagon is elevated and insulin signaling is dampened in late-stage lung TB mice, preventing insulin from exerting its anti-lipolytic effect." (PMID 36277179, 2022). "The inhibitory effect of insulin on hepatic glucose production is impaired during liver IR." (PMID 31920677, 2019). "Acute exercise could also indirectly activate the liver leptin-AMPK-ACC signaling pathway and increase insulin sensitivity, but it should be noted that irreversible liver lipid disorders are induced by a high fat diet." (PMID 24455748, 2013). "An important explanation for these incongruencies may be differences in the study population: we selected individuals with predominant muscle or liver IR, thus excluding insulin-sensitive individuals and individuals with combined muscle and liver IR, resulting in a smaller range of MISI and HIRI." (PMID 38493102, 2024). "Hence, in liver IR, impaired insulin-mediated suppression of VLDL assembly and secretion may contribute to elevated postprandial VLDL levels, while this suppression is likely better maintained in individuals with predominant muscle IR." (PMID 38493102, 2024). "Hence, we investigated whether G3BP1+/INS mRNA+ condensates could also be detected in beta cells within snap-frozen surgical specimens of living donors undergoing pancreatectomy for a variety of disorders of the exocrine pancreas." (PMID 40355555, 2025).
liver (continued). "First, the involvement of insulin and IGF-1 in colorectal carcinogenesis has been supported by experimental and clinical studies." (PMID 23349764, 2013). "Furthermore, liver IR has been characterized by elevated postprandial total TAG in response to an oral fat load, compared to muscle IR and insulin-sensitive individuals." (PMID 38493102, 2024). "The relationship between fatty liver and IOP was primarily linked directly rather than indirectly through insulin resistance." (PMID 36364718, 2022). "During chemotherapy, insulin treatment significantly reduces the effects of gastrointestinal tumours, and the efficacy of chemotherapy does not plunge." (PMID 36776356, 2022). "Meanwhile,it has been suggested that insulin may promote colorectal carcinogenesis directly by activating its own receptor, the receptors for IGF-I, or hybrid insulin/IGF-I receptors." (PMID 29793481, 2018).
peripheral neuropathy (66 papers, 2007 to 2026). A disorder affecting the peripheral nervous system. "Peripheral neuropathy increased the risk of ulceration (OR = 1.7; 95% CI = 1.1–2.6; p = 0.019), while insulin use was protective against amputation (OR = 0.1; 95% CI = 0.1–0.9; p = 0.049)." (PMID 38439010, 2024). "In multivariate analysis, peripheral neuropathy (p < 0.001) and insulin treatment (OR 2.04, 95% CI) were significantly associated with presence of foot ulcer." (PMID 33294430, 2020). "In their study population, presence of foot ulceration was 15% and they have found a significant association between foot ulceration and presence of peripheral neuropathy and insulin treatment." (PMID 33294430, 2020). "In multivariate analysis, peripheral neuropathy and insulin treatment were significantly associated with presence of foot ulcer." (PMID 26064190, 2015). "We considered a history of previous falls to be the most important confounding factor that studies needed to adjust for and gave additional credit to articles that controlled for some other factor such as age, insulin use or peripheral neuropathy." (PMID 40524408, 2025). "The contribution of insulin to the pathogenesis of peripheral neuropathy has recently been investigated, with an emphasis on differing or divergent exposures in T1DM and T2DM." (PMID 35631433, 2022). "Specifically, our patient was treated with insulin for two years and received a sufficient education on the correct use of the device, but his severe peripheral neuropathy compromised his ability to safely remove the needle." (PMID 33492465, 2021). "Peripheral neuropathy is associated with higher concentrations of circulating FGF-23, whereas patients treated with GLP-1 analogues or insulin have lower levels of circulating FGF-23." (PMID 32998751, 2020). "In the present study, we investigated the effects of crocin and safranal (alone or in combination with insulin) on peripheral neuropathy in diabetic rats." (PMID 26468467, 2015). "By blocking JAK-mediated phosphorylation of STAT proteins, JAK inhibitors help alleviate cytokine-driven inflammation, reduce insulin requirements, and relieve complications such as painful peripheral neuropathy, potentially preserving residual beta-cell function and improving glycemic control." (PMID 40534861, 2025). "•The mechanism of peripheral neuropathy was investigated in insulin resistance state." (PMID 35199097, 2022). "Similar changes in insulin signaling in the peripheral nerves may be involved in peripheral neuropathy in this study." (PMID 35199097, 2022). "GLP-1 RAs seem not to have a significant effect on peripheral neuropathy, compared to insulin-treated patients." (PMID 37231200, 2023). "The prevalence and incidence of peripheral neuropathy seemed to be higher in patients treated with insulin rather than OGLDs-treated patients." (PMID 24593991, 2014). "Insulin therapy and peripheral neuropathy were related to the non-amputation group in this study." (PMID 31396465, 2019).
inflammation (53 papers, 2012 to 2025). Aberrant reaction of the microcirculation characterized by movement of fluid and leukocytes from the blood into extravascular tissues. "The destruction of β-cells and decreased insulin production are closely associated with pancreatic inflammation." (PMID 40943103, 2025). "GlycA is associated with chronic inflammation of the pancreas and serves as a marker for predicting impaired insulin secretion." (PMID 38915894, 2024). "Furthermore, inhibition of insulin secretion during STZ-induced chronic pancreatic inflammation may be associated with attenuated expression of SPARC and thus mediated dysregulation of β-cell function in the diabetic pancreas." (PMID 26110898, 2015). "Current studies on Metrnβ have mainly focused on neurodevelopment, insulin resistance, beige fat thermogenesis, metabolism and inflammation related diseases." (PMID 37686413, 2023). "Chronic inflammation impairs the aging body in various ways (for example, insulin irregularity, hormonal and epigenetic changes, endothelial malfunction, and microvascular alterations)." (PMID 37476893, 2023). "Our goal was to investigate the mechanism of action of insulin in bowel inflammation and the relationship between insulin and the gut microbiota." (PMID 37491256, 2023). "As previously shown, IR in chronic HCV mainly results from an increased peripheral resistance to insulin activity which is triggered by proinflammatory cytokines and chronic hepatic inflammation." (PMID 32825571, 2020). "There are several studies suggesting that insulin modulates pulmonary allergic inflammation at all stages." (PMID 32117245, 2020). "In the current study, our data revealed that the effects of liraglutide on LPS-induced pulmonary inflammation, pulmonary edema, increase in insulin level, and ATII cell injury were significantly blunted by shRNA-TTF-1." (PMID 29950925, 2018). "Whereas, SAA plasma levels were positively correlated with insulin levels (p < 0.05), inguinal adipocyte size (p < 0.001), and liver inflammation (p < 0.01) only in late adulthood." (PMID 28686216, 2017). "Several indole derivatives produced by gut microbiota—including indole-3-acetate and indole-3-aldehyde—act as endogenous AhR ligands and have been reported to exert beneficial effects by modulating lipid metabolism, improving insulin sensitivity, and attenuating adipose inflammation." (PMID 40943373, 2025). "Excessive fat intake is the main reason inducing insulin resistance and adipose inflammation." (PMID 35743009, 2022). "Chronic systemic inflammation associated with VAT and the alterations in glucose and insulin may be connected to cognitive disturbances." (PMID 31554665, 2019). "LPS in turn is involved in the activation of toll-like receptor 4 (TLR4) in the Kupffer cells stimulating essential inflammatory cascade, which results in prolonged liver inflammation, liver damage, and impairment of insulin signaling by diminishing phosphorylation of the insulin receptor." (PMID 27367724, 2016). "Nevertheless, excessive ROS levels may cause oxidative stress and mitochondrial dysfunction, likely as a link between brain inflammation and defective insulin signaling." (PMID 27406855, 2016). "Silencing of the EPHX2 gene in mice has been shown to attenuate renal inflammation and albuminuria, whereas experimental and clinical data have shown that epoxyeicosatrienoic acids and genetic variations of the EPHX2 gene were directly associated with insulin sensitivity and glucose homeostasis." (PMID 34040693, 2021). "Cows with persistent postpartum uterine inflammation had higher serum concentrations of TNF-α, IL-6, leptin, but lower insulin and IGF-1 compared to normal and spontaneously recovered cows and there was a temporal association observed during the study period." (PMID 24209779, 2013).
immune dysfunction (40 papers, 2010 to 2025). "Abnormal insulin secretion or disordered insulin biofunction can lead to high blood glucose, which will cause vascular dysfunction and immune disorders, and even severe complications to various organs, including brain, eyes, and skin." (PMID 30120827, 2018). "For example, Type I diabetes (T1DM), an auto-immune disease characterized by immune-mediated destruction of insulin-producing beta cells, is enriched in our model." (PMID 36993954, 2023). "The pathological characteristics of T2D are complicated, including pancreas β-cells damage, decreased insulin sensitivity in target organs, inflammation, gut microbiota dysbiosis and immune disorders, and these are also potential therapeutic targets for T2D." (PMID 31952248, 2020). "T1DM results from a complex disease process in which genetic, environmental factors, and/or immune dysfunction lead to an autoimmune response, resulting in pancreatic β-cell destruction, depriving the organism from endogenous insulin." (PMID 31466386, 2019). "The mechanism(s) by which VSL#3 intervention attenuates immune dysfunction and resets insulin signalling are multiple, and certainly include attenuation of intestinal epithelial barrier dysfunction." (PMID 23029000, 2012). "Due to these fundamental immune modulations and induction of immune balance, this trial indicates that a single treatment with Stem Cell Educator therapy can give rise to long-lasting reversal of immune dysfunctions and improvement of insulin sensitivity in long-standing T2D subjects." (PMID 23837842, 2013). "Several mechanisms have been proposed for this increased susceptibility, including pre-existing immune dysfunction, a lack of metabolic flexibility due to insulin resistance, inadequate dietary quality or adverse interactions with antidiabetic treatments or common comorbidities." (PMID 35957811, 2022). "In addition, the improvements noted were the results of immunomodulation contributed by insulin, which has negative feedback of inflammatory stress caused by microbes, immune disorders, and chronic diseases." (PMID 33679687, 2020). "Relative Energy Deficiency in Sport (RED-S) has been reported in male and female elite athletes and impairs endocrine response (i.e., cortisol, insulin, IGF-1, adipokines, incretins), contributing to metabolic and immune dysfunction." (PMID 36615810, 2022). "Cortisol and other hormones such as insulin, IGF-1, modulated by RED-S also could contribute to immune dysfunction." (PMID 31686980, 2019).
bacterial infection (38 papers, 2011 to 2025). "The number of daily insulin injections is positively correlated with the risk of local bacterial infections." (PMID 41179869, 2025). "Significant changes in GLU levels were observed in infected golden pompano, probably due to impaired hepatic glucose metabolism caused by pathogenic bacterial infection, affecting insulin resistance and glucose metabolism." (PMID 36139883, 2022). "Impaired insulin signaling induces aberrations in phagocytic cells, which are crucial mediators for controlling and resolving bacterial infections." (PMID 38526063, 2024). "Our objective was to study the role of insulin and metformin in the placental inflammatory response and innate defense against common etiopathological agents of pregnancy bacterial infections, such as E. coli and S. agalactiae, in a hyperglycemic environment." (PMID 36982317, 2023). "In relation to their properties against bacterial infections, insulin limited the invasiveness of both E. coli and S. agalactiae into placental villous trees and diminished the extracellular E. coli growth." (PMID 36982317, 2023). "This review brings the new perspective that systemic insulin resistance represents an essential mechanism for overcoming the acute phase of bacterial infection." (PMID 33659253, 2021). "We and others have observed that bacterial infection and immune activation in Drosophila can drive disruption of systemic insulin signalling." (PMID 30910908, 2019). "In this review article, we summarized the recent progress in the development of label-free optical PSi-aptasensors for human diseases diagnosis such as bacterial infections, real-time monitoring of insulin and human α-thrombin." (PMID 31200538, 2019). "Authors suggested that insulin has the ability to compress the paracellular barriers of the airway epithelium, creating an airway metabolite barrier against bacterial infections." (PMID 29229986, 2017). "Of importance, T. cruzi infection was shown to influence the secretion by adipocytes of insulin-response regulatory adipokines and skin adipocytes also represent a source of antimicrobial peptides during bacterial infections." (PMID 27441553, 2016). "It was recently shown that Interleukin-6 (IL-6) plays a beneficial role in anti-inflammatory activity to against bacterial infections, and enhances insulin action immediately at early recovery." (PMID 22553973, 2012). "Another common cutaneous symptom of insulin application is a bacterial infection." (PMID 41179869, 2025). "For the molecular mechanism of Xuebijing treatment against bacterial infection, we found the requirement of insulin, p38 MAPK, Wnt, DBL-1/TGF-β, ELT-2, and PCD-related signals for the formation of the beneficial function of Xuebijing against bacterial infection." (PMID 36120363, 2022). "Additionally, this nanodiamond-delivered insulin is effective in wound healing and vascularization in patients with severe burns and other conditions and targets bacterial infections accompanying serious wounds." (PMID 35444547, 2022). "After we diluted the cell lysed samples after bacterial infection by 100 and 10,000 times and performed the colony assay, the reduced results of insulin pretreatment were still the same or even more significant (Figure 1A1,B1, with 100× dilution; Figure 1A2,B2, with 10,000× dilution)." (PMID 34946023, 2021). "Current progress in insect immuno-metabolic research reveals that the induction of insulin resistance might represent an adaptive mechanism during the acute phase of bacterial infection." (PMID 33659253, 2021). "Previous work in our lab suggests that during bacterial infection, flies may disrupt insulin signaling as a means of conserving energy for immune-related activities, leading to metabolic dysregulation." (PMID 32733472, 2020).